BRAF (B-Raf proto-oncogene, serine/threonine kinase)
Diseases named in the same sentence as BRAF in open-access papers (continued):
Sharing a sentence is not in itself a finding about the gene and the disease.
tumor (continued). "HRAS and BRAF mutation allele frequencies (range 11–46%; mean 29%) were consistent with somatically acquired mutations (i.e., admixed with normal stroma), which we confirmed in three CAA cases by laser microdissection (and PCR/Sanger sequencing) of separate tumor epithelium and stroma." (PMID 30741938, 2019). "Oncogenic activation of the BRAF-depending pathway, which may induce immune tolerance into the tumour microenvironment (i.e., by increasing the VEGF production) was poorly associated with mutations in genes that have been related to diminished clinical benefit of the treatment with BRAF inhibitors." (PMID 31581559, 2019). "Indeed, experimental evidence indicates that BRAF-inhibitors directly reduce the proliferation and viability of cancer cells, and indirectly prevent the metastatic process by modulating the chemokine milieu in the tumor microenvironment." (PMID 31762942, 2019). "Besides patients carrying a BRAF mutation, MIF inhibitors could technically be effective on many tumor types harboring different mutation profiles, providing therapeutic alternatives to patients whose tumors do not correspond to classical targeted therapies." (PMID 31013837, 2019). "Finally, we aimed at evaluating whether tumor side may have prognostic significance when considered alone or by multivariable analysis together with BRAF status, type of first-line chemotherapy, and the interaction of these two variables." (PMID 31036005, 2019). "BRAF V600E was found to influence the composition of the so-called tumour microenvironment modulating both solid (immune-cell infiltration) and soluble (chemokines) mediators, which balance characterize the ultimate behaviour of the tumour, making it more or less aggressive." (PMID 31762942, 2019). "Prolonged continuous targeting may intensify the emergence of resistance mechanisms and carries the risk of continuous drug toxicity; intermittent targeting may allow for the mutant BRAF subpopulation of cells to regrow to induce drug-resistant tumor progression." (PMID 31426419, 2019). "Our results show that DSF co-treatment with: a) MEK inhibitors may enhance tumour suppression; b) OxPt in CRC may counteract impaired response to cetuximab by KRAS/BRAF mutations and c) as a single treatment, TTM may be less effective than DSF and decreases the efficacy of the latter." (PMID 30792807, 2019). "However, there was no statistical difference in patient age, gender, tumor location, or BRAF mutation status between the groups (p > 0.05)." (PMID 31275248, 2019). "Therefore, the anti-tumor effects of these BRAF inhibitors are enhanced by co-administration of MEK inhibitors, and combined therapy with a BRAF inhibitor and MEK inhibitor is recommended as one of the first-line therapies for advanced BRAF-V600-mutated melanoma." (PMID 31514399, 2019). "These analyses revealed no KRAS/BRAF/GNAS/PIK3CA mutations in all tumor samples." (PMID 30116990, 2018). "Moreover, we investigated the KRAS/BRAF/GNAS/PIK3CA mutational status (mutational analysis for exon 2 of KRAS, exon 15 of BRAF, exons 9 and 20 of PIK3CA, and exons 8 and 9 of GNAS) of the original tumor (pancreatic head) and the recently resected tumors from the pancreatic body and tail." (PMID 30116990, 2018). "Although they use sensitive assay with a detection limit of at least 0.5% V600E tumor cells, the copy number of mutant versus wild-type alleles in their cells, cross-reactivity with non-target BRAF mutations, and KRAS mutation status were not clearly described." (PMID 29879227, 2018). "While the use of cfDNA for post-treatment surveillance has the advantage of the availability of somatic mutations in the resected tumor, if it were to become a sensitive diagnostic tool, expanded panels of genetic mutations would need to be detected to avoid false negatives in BRAF negative caners." (PMID 29761074, 2018).
tumor (continued). "The capacity of loss of CDX2—a differentiation-inducing transcription factor—to cooperate with the BRAF mutant to promote intestinal cell transformation is not surprising since CDX2 abnormalities have been associated with BRAF-driven serrated tumor development." (PMID 29652830, 2018). "Therefore, patients with a negative SLNB who harboured a BRAF/NRAS mutation experienced a hazard of disease relapse almost twice that of patients with BRAF/NRAS wild-type tumours." (PMID 29755118, 2018). "Having taken a novel and unbiased approach to classification, our findings suggest that BRAF and FGFR1 mutations are highly specific within glioneuronal tumours to each of the two molecular tumour groups we have identified, and may be well suited as markers for distinguishing them from one another." (PMID 29058119, 2018). "The patients with high-serum MMP-8 levels (>100 ng/mL) had poor cancer-specific survival, independent of tumour stage, grade, lymphatic invasion, patient age, BRAF VE1 immunohistochemistry, mismatch repair deficiency, Immunoscore and mGPS (multivariate HR 2.12, 95% CI 1.21–3.71, p = 0.009)." (PMID 29808017, 2018). "BRAF fusions have no known prognostic value, however, tumours bearing these mutations may in the future benefit from MAP kinase pathway inhibitors." (PMID 29098416, 2018). "However, declining plasma concentration of RAF inhibitors over time and low tumor tissue concentrations may lead to unwarranted paradoxical ERK activation in patients harboring non-V600 BRAF mutants." (PMID 29662630, 2018). "We found that BRAFV600E was present in 8 tumor tissues (50%): 5 from the aggressive group and 3 from the non-aggressive group, indicating that BRAF mutations may not be correlated with invasion and metastasis." (PMID 30285776, 2018). "Together, these studies indicate that detection of a negative BRAF mutation in the primary tumor may not necessarily reflect the BRAF mutation status of metastases." (PMID 29148538, 2018). "Consequently, in all four CRC cell lines tested, combination of AZ304 and Cetuximab caused a more potent inhibition of BRAF, ERK, AKT and mTOR signalling pathways, compared with single agents, providing a rationale for the observed synergy in anti-tumour effects." (PMID 29755114, 2018). "Moreover, combined quisinostat/flavopiridol treatment could be used as first-line treatment in CM patients that have a BRAF wild type tumor." (PMID 29464063, 2018). "However, let-7f was highly expressed in tumor tissues with BRAF-wildtype." (PMID 29713312, 2018). "No KRAS and BRAF mutations were identified in the same tumor." (PMID 28422723, 2017). "In particular, the BRAF V600E mutation (rs113488022) in exon 15, which occurs in 8-10% of colorectal tumors and is mutually exclusive with KRAS mutations, was found to be associated with a more aggressive tumor phenotype, lymph node metastasis, and high microsatellite instability (MSI)." (PMID 28708103, 2017). "Therefore we scaled our mouse treatment doses to therapeutically relevant human doses, we assessed the lowest level of drug dosage that could result in sustained suppression of BRAF-fusion driven tumor growth in vivo." (PMID 29156677, 2017). "Thus, the frequency of tumor-tissue EGFR M- and plasma cfDNA EGFR M+ patients is 4.0% (155/3834), which is higher than the frequencies of tumor tissue rare mutations such as ROS1, RET, BRAF, etc." (PMID 28052016, 2017). "Components of the pathway, including growth factor receptors, regulators of RAS, the RAS proteins themselves, BRAF, MEK1 and MEK2 are mutated in a variety of cancers, resulting in hyperactivation of ERK1/2 signalling which underpins the growth and maintenance of many tumour types." (PMID 28548464, 2017). "Using the short term ex-vivo treatment protocol we established that: 1) 3 μM of Selumetinib inhibits pERK1/2 phosphorylation in all tumours and the effect is independent of whether or not tumours harbour a KRAS or BRAF mutation." (PMID 28931905, 2017).
tumor (continued). "Furthermore, studies evaluating cost effectiveness of the various strategies have largely favoured universal testing, with initial IHC testing followed by BRAF mutation analysis for MLH1 absent tumours emerging as the most cost-effective approach." (PMID 28752083, 2017). "Beyond the outgrowth of mutant BRAF, we identified two additional genetic alterations in the resistant tumor that could contribute to EGFR TKI resistance: focal amplification of 7q31.2 encoding MET in the resistant tumor cells, a low frequency EGFRT790M mutation (14% variant frequency)." (PMID 28287179, 2017). "The close relationship between CIMP and BRAF mutation may drive carcinogenesis regardless of tumor location." (PMID 28623901, 2017). "In addition, the clinical significance of finding BRAF mutation using a high sensitivity technique in a low number of cells in the primary tumor is still unclear, especially when not confirmed in the metastatic sample." (PMID 28039443, 2017). "As we already suggested earlier, a subset of patients (showing gene mutations in PIK3CA, HRAS, KRAS, NRAS and BRAF or ALK translocation) could benefit from a systemic treatment with a PI3K, MEK, BRAF or ALK inhibitor in the case of unresectable or metastasized tumor stage." (PMID 29312620, 2017). "A few tumor sample may harbor a BRAF p.V600E mutation but the dominant gene expression pattern of this tumor sample is not a mutation like." (PMID 29479053, 2017). "However, the durability of response is limited and tumour progression occurs after 6-7 months of monotherapy or around 9 months of combination therapy, indicating the development of compensatory mechanisms that antagonize mutant BRAF and MEK inhibition." (PMID 29050198, 2017). "Indeed, AXL expression was increased in tumours growing on BRAF inhibitor monotherapy." (PMID 28606996, 2017). "Moreover, the consistency and growing list of BRAF/RAF gene fusions suggests these rearrangements to be informative tumor markers in molecular diagnostics, which could guide future treatment strategies." (PMID 28448514, 2017). "This is mainly due to the pre-screen procedure used in this study, the top ranking 96 tumours in the pre-screen procedure during the sample collection not only enriched for BRAF mutated samples, but also enriched for BRAF wild-type samples that are true BRAF-mutation-like subtype." (PMID 29479053, 2017). "However, the rate of cfDNA mutations in the patients without any prior KRAS/NRAS/BRAF/PIK3CA tumor mutations was 10-fold lower than the cutoff (0.002% ± 0.00014; N = 374)." (PMID 27852040, 2017). "As such, the detection of the heterozygous BRAF V600E mutation in samples containing < 50% of tumor cells may not be accurate." (PMID 29132392, 2017). "When it comes to targeted drugs directed specifically towards the tumour cells in CRC, the EGFR antibodies cetuximab and panitumumab are now often routinely added to the chemotherapy in advanced CRC, if the tumour cells are not harboring any KRAS or BRAF mutation." (PMID 29262612, 2017). "No patient with a BRAF-mutated tumor objectively responded to cetuximab-based therapy." (PMID 28507280, 2017).
tumor (continued). "Genomic DNA from primary tumour tissues of 1284 consecutively-collected patients with metastatic colorectal carcinoma (mCRC), originating from different geographical areas within Sardinia island, was screened for somatic mutations in KRAS, NRAS, BRAF, and PIK3CA genes." (PMID 27737711, 2016). "Furthermore, changes in the BRAF V600mut ctDNA concentration might be helpful for the interpretation of imaging results during immunotherapy where atypical tumor responses are more frequent." (PMID 27095081, 2016). "Of significance is the fact that KRAS and BRAF mutations are preferentially found as alternative molecular alterations and thus are not frequently observed in the same tumor suggesting that KRAS and BRAF have distinct roles in the development and progression of CRC." (PMID 27602501, 2016). "However, these expression profiles were independent of BRAF mutation status and did not correlate with either proliferation in vitro or with subcutaneous xenograft tumour establishment." (PMID 27835901, 2016). "In meta-analysis studies, the BRAF V600E mutation is reported to be associated with extra-thyroidal extension, advanced TNM stage, lymph node metastasis, multifocality, and recurrence, suggesting that PTC with a BRAF V600E mutation has more aggressive tumor biology." (PMID 27277113, 2016). "For example, mutations in FGFR1, BRAF, RET, MET, HER-2 occur in about 3% of all NSCLC, and since tumours bearing these mutations were already successfully treated with targeted therapies in other types cancers, it has been hypothesised that they might be effective in NSCLC as well." (PMID 27350784, 2016). "BRAF mutations have been found in various cancers including melanoma, colon cancer, and thyroid cancer, and in PTCs BRAFV600E mutation, a T1799A point mutation in the B-type Raf kinase gene is thought to be the most common genetic alteration related to tumor aggressiveness and poor prognosis." (PMID 27185169, 2016). "Specimen 2 consists of two morphologically different tumor nodules, an invasive adenocarcinoma, solid predominant type, which is positive for BRAF V600E mutation and a minimally invasive adenocarcinoma, nonmucinous tumor, which is negative for BRAF codon 600 mutation." (PMID 27597976, 2016). "Both tumor components were negative for BRAF and EGFR mutations (data not shown)." (PMID 27597976, 2016). "The BRAF mutation was found only in tumor samples but not in their normal counterparts." (PMID 26716505, 2016). "Moreover, the human BRAF pseudogene (BRAFP1) has been recently found overexpressed in various tumor types, suggesting that it may contribute to cancer development." (PMID 26895108, 2016). "Importantly, these feedbacks and cross-talk can shape the response of tumor cells to targeted therapies, which may be different depending on mutations in the pathway, such as in KRAS or BRAF genes." (PMID 26799289, 2016). "In contrast, if a BRAF mutation is identified, the lesion is presumably a borderline or low-grade tumor; thus conservative rather than radical surgery might be sufficient." (PMID 27421040, 2016). "Since PTEN also plays an important role in tumor cell migration and spreading, we speculated that miR-7 could not only reverse the resistance of BRAF inhibitors, but also suppress the invasion and migration of VemR A375 cells through up-regulating the expression of PTEN." (PMID 27448964, 2016). "“Non-classical” BRAF mutations may be responsible for tumor cell resistance to vemurafenib and dabrafenib, but increased sensitivity to sorafenib (multi-kinase inhibitor) and MEK inhibitors." (PMID 27276710, 2016). "Another approach might be the use of combination therapies that target tumor proliferation while also promoting immune infiltration, such as BRAF-targeted therapies or oncolytic viruses that have been demonstrated to replicate preferentially within cells with defective IFN signaling." (PMID 27782862, 2016). "CI did not reveal the anti-tumor effect in all 3 patients with BRAF mutation." (PMID 26486455, 2015).
tumor (continued). "Dr Girotti showed that BRAF inhibitors such as vemurafenib or dabrafenib, or MEK inhibitors, trametinib and cobimetinib, block the RAS-RAF-MEK-ERK pathway, inhibiting cell growth and increasing progression-free and overall survival in patients whose tumours carry BRAF mutations." (PMID 25932043, 2015). "Importantly, six of our cases (22%) had a BRAF mutation in the second-largest tumor when the largest tumor was BRAF-negative." (PMID 26448939, 2015). "In addition, BRAF mutant ctDNA as detected by ddPCR could be used diagnostically where the tumour block was unavailable." (PMID 26095797, 2015). "Tumor heterogeneity of BRAF mutated melanomas, including some areas without BRAF mutations, have been reported by a few groups, and could also be responsible for low BRAF-M%." (PMID 26141748, 2015). "We could compare the BRAF V600E status of different tumor foci using AS-PCR in 12 of our 14 cases." (PMID 25882744, 2015). "However, to the best of our knowledge, a possible association between MT1-MMP protein expression and molecular (KRAS/BRAF mutation status) and morphologic tumor characteristics (invasion pattern/budding) has so far not been investigated." (PMID 26106602, 2015). "By applying the same ‘exclusivity analysis’ to mutation data from other tumor types, however, we identified or confirmed other pairs of mutations—mutant KRAS and BRAF in COAD, mutant EGFR and NF1 in GBM, and mutant BRAF and NRAS in SKCM —that may be synthetically lethal in those tumors." (PMID 26047463, 2015). "The main findings were that KRAS mutation was associated with advanced disease stage, BRAF mutations were mainly found in right colon, PIK3CA was associated with poor tumour differentiation, MSI was more commonly seen in lower disease stage, larger and more poorly differentiated tumours." (PMID 25884297, 2015). "Side-by-side studies using comparable genetically engineered mouse models will be required to ascertain these effects, which could shed light on different selective constraints that KRAS- versus BRAF- mutant cells have for tumor initiation and progression in the intestinal epithelium." (PMID 26299805, 2015). "Recent studies have found that BRAF mutation is most likely not present in every cell of a given tumor and that the percentage of mutated alleles may vary regionally within the tumor." (PMID 26448939, 2015). "Furthermore, BRAF inhibition could contribute to the “autovaccination” of patients as tumor destruction leads to epitope exposition and immune effector elicitation." (PMID 25709607, 2015). "Considering that the in vitro inhibition of the BRAF downstream target MEK also affected MGL ligand expression, we assume that activating mutations in members of the MAPK pathway other than BRAF, such as KRAS and EGFR, may also cause aberrations in tumor cell glycosylation." (PMID 26172302, 2015). "A further important observation from mouse models and human CRC is that mutations activating KRAS and BRAF do not necessarily result in tumor formation in the intestinal epithelium, due to the existence of fail-safe mechanisms suppressing tumor growth after MAPK activation." (PMID 26299805, 2015). "For left colon, MSI and BRAF mutations could not be found in tumours from patients developing disease recurrence in stages II or III and were rare in those with disseminated disease." (PMID 25884297, 2015). "However, when the previous work within this field is taken into account, they support the hypothesis of a BRAF V600E specific inhibitory role within this tumor entity." (PMID 26065894, 2015). "Indeed here we show both in vitro and in an in vivo xenograft model that combined treatment with A3 and A4 antibodies is able to more potently induce receptor degradation and as a result to more potently sinergize with the BRAF/MEK inhibitors in tumor growth impairment and induction of apoptosis." (PMID 26208478, 2015).